H2AX (H2A.X variant histone)
Diseases named in the same sentence as H2AX in open-access papers (continued):
Sharing a sentence is not in itself a finding about the gene and the disease.
tumor (continued). "Because cisplatin kills tumor cells by inducing replication fork arrest and subsequently causing replication stress, we next explored whether cDOPEY2 impacted DNA damage in tumor cells by performing γ-H2AX staining." (PMID 34781999, 2021). "BRCA1 R1443* PDX tumors at endpoint for vehicle showed diffuse H2AX staining across the entire tumor, whereas combination treated tumors showed intense H2AX foci and entire cells positive for H2AX, with significantly more intense staining in the combination treated tumors." (PMID 34465787, 2021). "Highest numbers of dark-stained γ-H2AX-positive tumor cells were observed upon 195mPt-BP treatment." (PMID 33490949, 2021). "To investigate whether pericyte depletion increases the anti-tumor efficacy of TMZ, we determined the level of phosphorylated histone H2A variant (γ-H2AX), a DNA damage marker, in GBM xenografts." (PMID 34239070, 2021). "Radiation dose to the tumour and lung contributed to the in vivo induction of γ-H2AX foci." (PMID 32899789, 2020). "In our study, the increase of γ-H2AX after drug administration was particularly higher in dogs who experienced a clinical response and the results confirmed that γ-H2AX can be useful for elucidating the pharmacodynamics of cytotoxic drugs and tumor targeting agents in dogs." (PMID 32133044, 2020). "We found that irradiation had little effect on γ-H2AX expression in both cells and tumor tissues." (PMID 32364222, 2020). "ɣ-H2AX immunohistochemistry, performed as a biomarker of DNA DSBs, showed low levels background staining in talazoparib treated tumours and high levels of positive staining in both the LuTate and combination treated tumours." (PMID 32576907, 2020). "Interestingly, γ H2AX has been reported to be a tumor suppressor because of its role in the maintenance of genomic stability." (PMID 32784458, 2020). "Furthermore, reduced γ-H2AX expression, lower DNA fragmentation and decreased cell death fraction was found in tumor cells under hypoxia after IR exposure." (PMID 33318475, 2020). "Furthermore, γ-H2AX and cleaved caspase-3 expression were significantly increased in both miR-320c- and oxaliplatin-treated tumor groups." (PMID 33041328, 2020). "Whether high levels of pan-nuclear γ-H2AX are generated in patients or in human tumor samples following administration of cytotoxic doses of chemotherapeutics remains to be established." (PMID 30871194, 2019). "However, in the secondary tumor, very low level of gamma-H2AX staining was observed in all groups (P > 0.05)." (PMID 30873170, 2019). "Alternatively, previous studies have suggested that increased H2AX expression may increase tumor sensitivity to chemo/radiotherapy in cancers." (PMID 30285798, 2018). "However, histone γ-H2AX expression levels were reduced, suggesting that in the si-hVDAC1-treated residual “tumours”, chromosomal DNA damage was reduced." (PMID 30544833, 2018). "It has been known that Bclaf1 is a H2AX-dependent tumor suppressor." (PMID 29795334, 2018). "Since tumor organoids exhibited cellular structure similar to tumor tissue, we demonstrated that drug accessibility and uptake occurred in the deepest area at the core of tumor organoids, indicated by elevated γ-H2AX foci, a DNA damage response marker." (PMID 30353124, 2018).
tumor (continued). "Analysis of γ-H2AX in tumor biopsies is most typically done by immunofluorescent staining." (PMID 28158293, 2017). "In tumor cells with low Nrf2-antioxidant response after treatment, the levels of reactive oxygen species remain high, H2AX is efficiently degraded, further reducing repair of DNA damage induced by the drug, tumor cell apoptosis is subsequently increased, and patient survival improved." (PMID 29270905, 2017). "Similar results were also found via a γH2AX foci formation assay, at both 6 h and 24 h post-IR treatment, the percentage of primary-culture tumor cells containing γ-H2AX foci in the combined treatment group was obviously higher than that of the IR alone group (p < 0.05)." (PMID 28489060, 2017). "The high resolution of these images allowed us to overlay our dose map onto individual p-H2AX-positive cells to quantify dose response, an approach that can be extended to quantify the dose to specific areas such as blood vessels, tumor nests, or hypoxic regions." (PMID 28302144, 2017). "While, the mechanism by which IGPR-1 regulates phosphorylation of histone H2AX needs further investigation, the present data demonstrate that IGPR-1 by modulating phosphorylation of histone H2AX acts to reduce the sensitivity of tumor cells toward the DNA-damaging agent, doxorubicin." (PMID 28920928, 2017). "H2AX protein was clearly detected in fibroblasts and epithelial cells of LumA tumours." (PMID 27006338, 2016). "Our results show that the combination of lurbinectedin and gemcitabine induced a significant increase of γ-H2AX levels [a surrogate marker of DSBs] and clear caspase-3 activation (apoptosis induction), which were recorded in two different tumor xenografts after 24 h of drug treatment." (PMID 27780828, 2016). "Indeed, the high capacity of forming DDR foci results in tumour resistance to chemotherapy and γ‐H2AX blocking peptides enhance cell death of irradiated resistant tumour cells." (PMID 27006338, 2016). "Furthermore, a statistically significant difference in induction of DNA damage was seen between most of the tumor cell lines and normal cells, as evidenced by γ-H2AX levels." (PMID 27331622, 2016). "With these factors in mind, we propose that SRSF1 may also rely on modulating H2AX signal to sustain the tumorigenicity in some SCLC tumor patients." (PMID 27093186, 2016). "Moreover, the extent of H2AX downregulation in these patients is a reliable indicator of cancer cell apoptosis, tumour chemosensitivity and patient survival." (PMID 27006338, 2016). "The development of protocols to better cut out high levels of endogenous γ-H2AX foci may help the analysis to explore DNA DSB repair as a robust parameter to determine responses of tumor cells to radiation." (PMID 27257868, 2016). "Furthermore, work developed in vivo in subcutaneous tumours and normal skin showed the same correlation between the intensity of γ-H2AX and the dose." (PMID 25799425, 2015). "Moreover, the 1, 3 and 5 years tumor-free survival after LT were much worse for high-γ-H2AX than low-γ-H2AX expression group." (PMID 25537504, 2015). "The evaluation of γ-H2AX levels may not only allow for the monitoring of the efficiency of anticancer treatment but also predict tumor cell sensitivity to DNA damaging anticancer agents and toxicity of anticancer treatment toward normal cells." (PMID 26618801, 2015). "We also studied whether the presence of a tumour could modify the response of brain tissue to synchrotron radiation and lead to a different degree of γ-H2AX formation." (PMID 25799425, 2015). "However, the mean number of the background, induced or residual amount of the γ-H2AX foci in the group with stage IV has the tendency to be always lower than that of the group with the tumor stage III." (PMID 26541290, 2015).
tumor (continued). "Those reasons lead us to hypothesize that the presence of the C6 glioma in the right hemisphere of the brain could modulate the formation of γ-H2AX foci after synchrotron microbeam irradiation through tumour-induced bystander signals." (PMID 25799425, 2015). "To further investigate whether the tumor growth inhibition was related to DNA damage and autophagy, we confirmed the presence of γ-H2AX and LC3 expression in the tumor tissue using immunohistochemical staining." (PMID 25105411, 2014). "Significant roles for H2AX in both V(D) J and class switch recombination suggest that optimal H2AX function may be particularly important in preventing tumor formation in lymphoid cells." (PMID 24069324, 2013). "Tumour cell lines can express higher endogenous amounts of γ-H2AX." (PMID 23936236, 2013). "And finally, preliminary experiments with nude mice xenografted with LNCaP cells showed that (S)-2 was capable of reducing the tumor volume and increasing γ-H2AX levels within tumor cells in vivo as the best evidence for drug-induced caspase activation and DNA damage." (PMID 23469273, 2013). "Our study demonstrated that the neutral comet assay and γ-H2AX foci assay could be used to assess the radiosensitivity of 12C6+ in human tumour cells." (PMID 24133390, 2013). "Importantly, preliminary data with nude mice xenografted with LNCaP cells showed that (S)-2 prompted a decrease in the tumor volume and an increase in H2AX phosphorylation within the cancer cells." (PMID 23469273, 2013). "We have recently reported that untreated normal or tumor cells in culture exhibit a “background” level of DNA damage signaling (DDS) revealed as histone H2AX phosphorylation on Ser139 and activation of Ataxia Telangiectasiamutated protein kinase (ATM) through phosphorylation on Ser1981." (PMID 22498490, 2012). "While there are many factors which may govern tumor and patient response to therapy, some evidence exists that γ-H2AX may be a useful predictor of acute and late radiotherapy induced side-effect in cancer patients." (PMID 22170789, 2012). "The persistence of γ-H2AX foci in cells hypersensitive to DNA damaging agents has prompted extensive research into the application of γ-H2AX as a biomarker to predict both tumor response and acute and delayed side effects in cancer patients receiving clinical radiotherapy and/or chemotherapy." (PMID 22170789, 2012). "Monitoring γ -H2AX levels in a patient's circulating tumor cells (CTCs) following cancer treatment has been evaluated and may be a promising technique for following the pharmacodynamic effects of anticancer therapies." (PMID 21325706, 2011). "Whether these proteins are also involved in the modulation of H2AX levels in tumor cells remains to be tested." (PMID 18616816, 2008). "The fact that soluble H2AX induces apoptosis in tumor cells opens new avenues for cancer therapy." (PMID 18616816, 2008). "The results showed that tumor sections in the combination group displayed significantly lower levels of mitotic activities as determined by a pathologist (Y.L.), lower levels of Ki67 labeling positivity, higher levels of cleaved caspase‐3, and higher levels of γ‐H2AX." (PMID 41236163, 2026). "Hence, the observed anti-GBM action by BA could be attributed, to a greater or lesser extent, to its tumor-suppressing potency associated with GFAP, Ki67, Nop10, and H2AX expressions." (PMID 39821858, 2025). "Additionally, ELANE has been shown to upregulate γ-H2AX, a robust biomarker of DNA damage, thereby linking its activity to the induction of mitochondrial dysfunction and further amplification of apoptotic signaling in tumor cells." (PMID 40748972, 2025). "In parallel, clinical trials could assess the combination of PARP inhibitors with NLRP3-targeted therapies in patients with high NLRP3 expression, evaluating treatment efficacy by monitoring tumor progression, DNA repair markers (e.g., γ-H2AX), and patient response rates." (PMID 40718836, 2025).
tumor (continued). "Furthermore, the results of the IHC assay revealed that, in comparison to the control group, tumor tissues treated with flavokawain C exhibited a significant increase in γ-H2AX expression levels, confirming that flavokawain C treatment induced substantial DNA damage." (PMID 38460052, 2024). "Therefore, the role of H2AX in tumour progression is still intriguing." (PMID 38402225, 2024). "We, therefore, conclude that loss of H2AX might contribute to cancer progression once tumour cells have lost the normal responses to DNA damage, but not before." (PMID 38402225, 2024). "The inhibition of γ-H2AX could lead to the inhibition of mitotically active tumor cells." (PMID 38502354, 2024). "Moreover, as demonstrated by immunohistochemical (IHC) analyses performed in mice‐derived tumor sections, FK866 promotes a reduction of TRF2 expression, associated with increased levels of H2AX phosphorylation (γH2AX) and 8‐hydroxyguanine (8‐OHdG), and decreased Ki67 proliferation marker." (PMID 37858982, 2023). "Moreover, the CSP/Ola NPs could amplify DNA damage by released Cb and inhibit the activation of Poly(ADP-ribose) polymerase (PARP), promote the upregulation of γ-H2AX, thereby blocking the DNA repair pathway to sensitize tumor cells for PDT." (PMID 37836815, 2023). "Moreover, γ-H2AX+ area in the tumour tissue was increased by neutralising IFNγ treatment." (PMID 37056922, 2023). "Moreover, after irradiation of human HNSCC xenografted tumours, the residual γ-H2AX foci could predict the radiation response." (PMID 35055060, 2022). "In addition, nintedanib increased the phosphorylation of H2AX in the primary tumour cells derived from KIT‐V559D and KIT‐K642E GIST patients, which suggested that nintedanib could induce apoptosis in part through DNA double‐strand breaks." (PMID 35194937, 2022). "Also, H2AX plays a vital role in regulating tumor cell proliferation and angiogenesis." (PMID 34497156, 2021). "Moreover, we demonstrated also a clear increase of PARP cleavage in all the triple combination tumor samples compared with the other groups, in line with in vitro data showing increased apoptosis, paralleled by induction of DNA damage, measured as H2AX protein phosphorylation." (PMID 33032653, 2020). "In addition, the expression of phosphorylated H2AX was significantly higher (p < 0.05) after thermo-chemotherapeutic treatment compared to either therapy alone and the untreated control tumors on day 9 after the first tumor therapy." (PMID 32916798, 2020). "Mechanistically, mesima significantly enhanced radiotherapy efficiency by inhibiting tumor cell survival through inducing apoptosis (assessed via annexin V), impairing cell cycle regulation (shown by flow cytometry), and reducing radiation-induced DNA damage repair (measured via γ-H2AX foci)." (PMID 32013255, 2020). "Therefore, we propose that phosphorylation of H2AX by PKM2 to initiate DDR may act as an adaptive response in tumor cells exposed to genotoxic stress." (PMID 29312595, 2017).
tumor (continued). "Furthermore, as reported in previous studies using human tumor cell lines, analysis of γ-H2AX using flow cytometry might be a better method to evaluate radiosensitivity of canine cancer cells." (PMID 27257868, 2016). "In addition to GI toxicity to curative RT, we analyzed whether the γ-H2AX and 53BP1 foci assays allowed to discriminate between tumor stage (II, III or IV) or TRG after RT of RC patients." (PMID 26541290, 2015). "Given that SUV39H2 is significantly upregulated in various types of tumour tissues, it is possible that constitutive SUV39H2 overexpression in cancer cells may cause aberrant γ-H2AX expression, and that cancer cells might acquire more malignant phenotype, including chemo- and/or radioresistance." (PMID 25487737, 2014). "Analysis of γ-H2AX foci in different cultured tumor cell lines has shown that DSB damage plays a prominent role in the instability of telomeres in tumor cells, and our results support the idea that DNA damages or shortening of telomeres may also lead to elevated numbers of telomere fusions." (PMID 22916246, 2012). "In each tumor line, while themajority of the cells contained less than 10 foci per cell, there was a substantialfraction of cells that contained larger numbers of γ-H2AX foci, up to about 50 per cell, creating a long tail in thedistribution and leading to large standard deviations from the average." (PMID 20157510, 2009). "Therefore, since counting γ-H2AX foci in interphase tumor cells can provideonly limited information, studies in metaphase cells were performed toallow visualization of truly informative foci by avoiding at least some ofthese problems, such as proliferative status and focal variability." (PMID 20157510, 2009). "However, it needs to be shown whether recording of γ-H2AX will be an advantage over conventional gel electrophoresis for monitoring residual damage in tumour cells." (PMID 12888835, 2003). "The results demonstrated a significant increase in the expression levels of γ-H2AX, p-STING, and p-IRF3 in the tumor tissues of mice treated with CuB." (PMID 40896699, 2025). "IHC analysis demonstrated markedly reduced Ki-67 expression and elevated γ-H2AX levels in the GLS-knockdown group following IR treatment, indicating an augmented anti-tumor efficacy." (PMID 40308578, 2025). "CuB treatment significantly suppressed tumor growth in OS-bearing mice, and immunohistochemical analysis confirmed the upregulation of γ-H2AX and activation of the STING pathway in tumor tissues." (PMID 40896699, 2025). "In our study, upregulation of miR-20b enhanced γ-H2AX levels and reduced CCND1 expression following radiotherapy, ultimately suppressing tumor growth." (PMID 41395621, 2025). "IHC characterization of CD31 (tumor neovasculature), PSMA, and γ-H2AX (DNA double-strand break) was conducted from the cohorts after 8 days posttreatment." (PMID 39324008, 2024). "In vivo studies also pointed out the effects of hinokitiol on the inhibition of xenograft tumour growth in association with DNA damage and autophagy, as shown by the expression of γ-H2AX and LC3 in the tumour tissue." (PMID 38397967, 2024). "Analogously with our previous observations in MDA-MB-468 cells, we found that reducing LDHC expression in BT-549 cells increased the expression of the DNA damage marker phopsho-γ-H2AX and cleaved PARP, indicating that LDHC silencing induced tumor cell death." (PMID 39001513, 2024). "Immunohistochemistry revealed only weak upregulation of DNA damage markers (γ‐H2AX) due to HMGA1 interference alone, but olaparib treatment led to significant DNA damage in tumours with HMGA1 knockdown." (PMID 39690136, 2024). "We found that the designed compounds significantly upregulated the expression of γ-H2AX in tumor cells, inducing DNA damage while reducing PARP levels, thereby weakening the DNA damage repair capacity of tumor cells and leading to apoptosis." (PMID 39598828, 2024).